BRCA1 (BRCA1 DNA repair associated)
Diseases named in the same sentence as BRCA1 in open-access papers (continued):
Sharing a sentence is not in itself a finding about the gene and the disease.
breast cancer (continued). "However, the BRCA1 rs1799950 G variant described as benign in hereditary breast cancer, was protective in our study, in agreement with other sporadic breast cancer studies in European populations." (PMID 33126731, 2020). "There is not enough evidence to suggest tailored recommendations for dietary habits or weight management among women with BRCA1/2 pathogenic variants compared to the general population for ovarian and breast cancer risk-reduction, and physical activity recommendations should remain the same." (PMID 32165993, 2020). "Consequently, we conducted a two-stage study to systematically describe the BRCA1/2 spectra of Chinese women by direct sequencing in familial breast cancer patients and validated the candidate variants in multicancer-type samples." (PMID 32879886, 2020). "Race- and ethnicity-specific logistic regression burden tests adjusted for age at diagnosis of first breast cancer, histology, presence of first- or second-degree relatives with breast cancer, and prior testing for BRCA1/2 genes were used to test for associations with SBC." (PMID 33409458, 2020). "Thus, over 80% of hereditary BRCA1-mutated breast cancers are classified as TNBC and about 15% of TNBCs occur in carriers of a BRCA germline mutation (gBRCA)." (PMID 32210163, 2020). "Furthermore, previous researchers discovered that the high expression of the breast cancer susceptibility gene BRCA1 leads to a long life in insects." (PMID 32424344, 2020). "This is the reason why inhibition of DNA-dependent protein kinases (DNA-PKcs) involved in DDR and NHEJ pathways could be a new promising target in BRCA1-deficient breast cancer treatment." (PMID 32370233, 2020). "Similarly, while HR-deficient breast cancers only display a ~3-fold higher mutation burden, this correlates with a 20–40-fold increased cancer risk for carriers of BRCA1/2 mutations." (PMID 32358516, 2020). "BRCA1 is a well-characterized tumor-suppressor gene, which is involved in various cellular functions and women who carry a mutated BRCA1 allele are at higher risk of developing breast cancer." (PMID 32117726, 2020). "Women with a BRCA1 or BRCA2 mutation have a strongly elevated risk of developing breast cancer." (PMID 32333294, 2020). "BRCA1 gene mutation in women accelerates breast cancer at a younger age." (PMID 32824813, 2020). "Furthermore, physical activity is associated with a significantly delayed onset of breast cancer among BRCA1 and BRCA2 mutation carriers." (PMID 33134306, 2020). "To explore the utility of BRCA1 promoter methylation screening for breast tumors in Pakistan we investigated the frequency of BRCA 1 promoter methylation and its association with expression changes of BRCA1 and certain morphological features suggestive of breast cancer in a small cohort of patients." (PMID 32856871, 2020). "Besides breast cancer, a dysfunction in BRCA1/2 is also proven to be associated with an elevated risk of occurrence of other cancers, such as ovarian, pancreatic, prostate, and stomach cancers." (PMID 32300589, 2020). "Indeed, the lifetime risk to develop breast cancer is approximately 52–72% among BRCA1 mutation carriers and 45–84% among BRCA2 mutation carriers." (PMID 33198203, 2020). "There is a pressing need to better understand this type of cancer at the genomic level from the early premalignant stage through to tumor progression and metastasis stage in order to develop effective strategies for the prevention and treatment of BRCA1-associated breast cancer." (PMID 32978388, 2020). "Meanwhile, overexpression of PFKP may serve as an independent poor prognostic factor for patients with breast cancer, which provides an important basis for targeting PFKP in breast cancer patients with BRCA1 or ZBRK1 deficiency." (PMID 32470015, 2020). "This study suggests that the targeting of Rho proteins could be an effective therapeutic strategy for basal-like and BRCA1-mutated breast cancer." (PMID 33162807, 2020).
breast cancer (continued). "Germline BRCA1 gene mutations are reportedly associated with breast cancers." (PMID 31908633, 2020). "A new small inhibitor of Rho proteins, Y16, could also be tested in combination with Rhosin to study the potential of Rho as therapeutic targets for basal-like and BRCA1-mutated breast cancer." (PMID 33162807, 2020). "However, in women carrying a harmful BRCA1 mutation this is elevated to 60% lifetime risk of developing breast cancer and 44% risk of developing ovarian cancer." (PMID 33015058, 2020). "The empirical process used to fill this gap in relation to BRCA1/2 variant detection using WES provided unique insights incorporated into a pathology-supported genetic testing algorithm for return of research results to Kenyan breast cancer patients." (PMID 32231682, 2020). "In Cyprus, approximately 9% of triple-negative (negative in common breast cancer receptors—estrogen, progesterone, and human epidermal growth factor receptor 2 (HER2) receptors) breast cancer (TNBC) patients carry inherited mutations in the BRCA1/2 breast cancer (BC) susceptibility genes." (PMID 33120919, 2020). "Studies identifying association of BRCA1 mutation with haplogroup M in China and haplogroup X in Europe have suggested a role of these haplogroups to present population-specific alterations in genes conferring risk to familial breast cancer." (PMID 32210009, 2020). "Women with BRCA1/2 mutation who consider OC use have to be informed that this method may lead to an increase in breast cancer risk." (PMID 32140806, 2020). "However, inherited BRCA1/2 mutations only account for ~5.3% of all breast cancers and <15% of TNBCs3,17." (PMID 32555285, 2020). "Indeed, female individuals who carry a BRCA1/2-germline variant have a lifetime risk of developing breast cancer of up to 87%." (PMID 32087690, 2020). "Germline pathogenic variants in BRCA1/2 are highly penetrant for breast cancer." (PMID 32655641, 2020). "FANCD2 overexpression conferred resistance to PARPi in BRCA1/2-mutated breast cancer cell lines." (PMID 32563252, 2020). "More recently, data had shown that specific breast cancer treatment may be informed by the BRCA1 or BRCA2 mutation status." (PMID 32733560, 2020). "It is important to note that genetic susceptibility to EOC cancer does not exist in isolation, and variants conferring increased ovarian cancer risk also often increase the risk of developing other cancers—most notably breast cancer in BRCA1 and BRCA2, and colon cancer in Lynch syndrome." (PMID 33086730, 2020). "Breast cancer risk based on BRCA1 mutation carrier status will be greatly increased." (PMID 31908633, 2020). "In addition, the risk of breast cancer in probands carrying BRCA1/2 gene mutations has been changing over the years and this has been attributed to modifiable lifestyle-related factors." (PMID 33212987, 2020). "In 2005, PARP inhibitors were shown to suppress BRCA1/2-deficient tumors in breast cancer." (PMID 33182492, 2020). "Therefore, this study aimed to investigate the prevalence of MF/MC breast cancer in BRCA1/2 mutation carriers, with exploration of the clinicopathological characteristics of all tumours occurring in these patients." (PMID 32022473, 2020). "Overall, the present study not only enriched the pathogenic variant spectrum of BRCA1/2 but also suggested that a high-risk Chinese population of breast cancer might benefit from genetic screening using these recurrent loci." (PMID 32879886, 2020).
breast cancer (continued). "Thirty of the 78 individuals selected by convenience in the six families presented the mutation BRCA1 3450del4 six of whom developed breast cancer, one, ovarian cancer, one ovarian and breast cancer, and one prostate cancer; 21 did not present any type of neoplasm at the time of the study." (PMID 32220173, 2020). "In breast cancer with BRCA1 mutations, metformin inhibits RANKL and sensitizes CSCs to denosumab." (PMID 33014829, 2020). "In Africa, the pathogenic variant BRCA1: c.4065_4068del, observed in one patient of our cohort (33 aged), was previously observed in a 38‐aged Algerian and a 28‐aged Sudanese breast cancer patients." (PMID 32959997, 2020). "Therefore, we can preliminarily conclude that there are similarities between BRCAness and germline BRCA1 mutation in clinicopathological characteristics of breast cancer." (PMID 33273622, 2020). "Olaparib (LYNPARZA, AstraZeneca and Merck) was the first PARP inhibitor to receive FDA approval for indications in breast cancer and pancreatic cancer, and has since been approved for metastatic breast cancer in patients with germline BRCA1 or BRCA2 (gBRCA1/2) mutations." (PMID 32295316, 2020). "About 5–10% of breast cancers are caused by a gene mutation in BRCA1 and BRCA2." (PMID 32824813, 2020). "They found an increase in breast cancer risk for BRCA1 mutation carriers who started OC before the age of 20 years (OR = 1.45; 95% CI 1.20–1.75; p = 0.0001) and a non-significant increase for carriers who started between 20 and 25 years of age (OR 1.19; 95% CI 0.99–1.42; p = 0.06)." (PMID 32140806, 2020). "Due to the DNA translocase activity, SMARCAL1, a member of SNF2 family, could reverse the nascent DNA degradation induced by FANCD2 deficiency in BRCA1/2-mutated breast cancer cells." (PMID 32563252, 2020). "In addition, we also analyzed HERVs that were associated, by localization, with breast cancer development genes (BRCA1, CCND1, ATM, NBS1/NBN, RAD50, KRAS, PI3K/PIK3CA)." (PMID 33194615, 2020). "Decreased expression of BRCA1 accelerated the growth of malignant mammary cells and was associated with high-grade, advanced lymph node stage, larger size and vascular invasion in breast cancer." (PMID 31763681, 2020). "Using the survival analysis, we found that CCNE1, NPBWR1, A2ML1 and TTK might act critical functions in the oncogenesis and progression of BRCA1/2-mutant breast cancer, reflected by their diagnostic efficacy for BRCA1/2 mutations and prognostic value as well." (PMID 31998560, 2020). "Furthermore, Moskowitz reported that the cumulative incidence of breast cancer by the age of 50 is comparable with the risk of BRCA1 mutation carriers for childhood HL survivors." (PMID 32733794, 2020). "Breast cancers with loss-of-function mutations in BRCA1 or BRCA2 genes are deficient in the HR (Homologous Recombination) pathway that manages the repair of DNA DSBs (Double Strand Breaks); hence, they are exquisitely sensitive to poly(ADP ribose) polymerase (PARP) inhibitors." (PMID 32903519, 2020). "In summary, a multifaceted role of BRCA1 in breast cancer-related NER may be underlined by the following chain of events." (PMID 32013256, 2020). "Several PARPis are now approved for the treatment of BRCA1/2-mutated ovarian and breast cancers." (PMID 32029902, 2020). "Women with BRCA1/BRCA2 mutations had very high risk to develop breast cancer." (PMID 32802855, 2020). "Goals: BRCA1/2 mutations are associated with bilateral breast cancer." (PMID 32117708, 2020). "BRCA1 gene deficiency has been associated with basal-like breast cancer." (PMID 33162807, 2020). "Are pathogenic BRCA1 mutations associated with breast cancer recurrence?" (PMID 33391340, 2020). "It is estimated that about 5% of all breast cancer cases are associated with BRCA1 mutations." (PMID 32471217, 2020). "In addition, we found that BRCA1 mutation increased MFN1/2 expression in breast cancer patient‐derived xenograft (PDX) models." (PMID 32195105, 2020).
breast cancer (continued). "The BRCA1 mutations account for approximately 5% to 10% of all breast cancer." (PMID 32235451, 2020). "Therefore, our newly characterized Bard1‐deficient, orthotopic metastasis model can be used to accelerate the evaluation of PARP inhibitor efficacy in metastatic breast cancers harboring sensitizing BRCA1/2 pathway mutations." (PMID 32730698, 2020). "BRCA1 or 2 mutations may convey lifetime (to age 80) risks of breast cancer of up to 72% and 69%, respectively, and 44% and 17% risks of ovarian cancer." (PMID 32812179, 2020). "In addition, epidemiological data have shown that prophylactic oophorectomy in women with BRCA1 mutations reduces the incidence and recurrenceof breast cancer by 75%." (PMID 34803264, 2020). "The most important risk factors for breast cancer include female gender, age (30 years old and older), positive family history for breast cancer, and familial genetic mutations, including mutations in the breast cancer A1 (BRCA1) and BRCA2 genes." (PMID 32964011, 2020). "Recently, the EMBRACA and the OlympiaD trials have demonstrated that PARP inhibitor treatment using olaparib or talazoparib improves progression-free survival as compared to standard chemotherapy in advanced breast cancer patients that harbor a germline BRCA1 or BRCA2 mutation." (PMID 32934773, 2020). "Several clinical trials using PARPi including Olaparib, Veliparib, Rucaparib as monotherapy for the treatment of patients with germline BRCA1/2 mutation tumors including advanced breast cancer, ovarian cancer, pancreatic cancer and prostate cancer presented significantly antitumor effect." (PMID 33628188, 2020). "Approximately 80% of hereditary breast cancer cases develop due to the mutations on BRCA1/2 genes." (PMID 33488844, 2020). "Locally, we have observed that adherence to breast cancer risk management of BRCA1/2 PV/LPV carriers is much higher than ovarian cancer risk management – warranting further investigation into the support and informational needs of carriers to make risk management decisions." (PMID 33110458, 2020). "This suggests that inflammasome inhibition could serve as a therapeutic target for the treatment of BRCA1‐associated breast cancer." (PMID 32195105, 2020). "In addition, genetic testing of breast cancer patients revealed that the population which is of African or Bahaman decent showed higher frequencies of BRCA1 and BRCA2 mutations." (PMID 32824813, 2020). "There are many risk factors for developing breast cancer, for example, the occurrence of mutations in the BRCA1 and BRCA2 genes, hormone therapy during menopause, first menstruation at an early age, late motherhood or no children, older age, and a positive family history of breast cancer." (PMID 32015564, 2020). "Moreover, TNBC often displays molecular and clinical characteristics similar to DNA repair-associated breast cancer type 1 (BRCA1)-deficient breast cancer cases." (PMID 32456160, 2020). "Moreover, we also complied BRCA1/2 mutation status of TCGA breast cancer datasets from different sources (cBioPortal and TCGA accessible data) and further analyzed the association with the KEGG oxidative phosphorylation pathway." (PMID 32400970, 2020). "BRCA1/2 are recognized as the most commonly mutated genes in hereditary breast cancer cases." (PMID 32866190, 2020). "The genetic risk of breast cancer is modelled through estimates of mutations in BRCA1 and BRCA2 genes and an unknown dominant gene." (PMID 32226220, 2020). "Similarly, negative regulatory role of Akt on homology-mediated repair was shown for BRCA1-deficient breast cancer cells." (PMID 33266502, 2020). "Germline mutations in BRCA1/2 (gBRCAm) predispose to ovarian cancer and breast cancer." (PMID 32563252, 2020).
breast cancer (continued). "Moreover, BRCA1 c.3257del was the most frequent variant observed in Chinese sporadic breast cancer and showed increased proliferation of BRCA1c.3257del-overexpressing triple-negative breast cancer cell lines (MDA-MB-231) in vitro." (PMID 32879886, 2020). "Early in 2002, a cohort study containing 11,847 individuals from 699 families of the Breast Cancer Linkage Consortium (BCLC) found that BRCA1 pathogenic mutations might increase the risk of abdominal cancers in women or pancreatic cancer in men." (PMID 32879886, 2020). "Furthermore, the RANKL/RANK signaling in mammary progenitor cells is critical for the initiation and progression of breast cancer susceptibility gene 1 (BRCA1) mutation-driven mammary cancer." (PMID 32047573, 2020). "In summary, our study suggests that the prognostic value of BRCA1/BRCA2 germline mutations in breast cancer patients who were preselected for genetic screening and treated with neoadjuvant or adjuvant chemotherapy depends on the molecular subtype with a survival benefit only in women with TNBC." (PMID 32341426, 2020). "Five breast cancer cell lines were positive for pathogenic BRCA1/2 mutations." (PMID 32620799, 2020). "The present finding that RAD52 S346X reduces cancer risk in BRCA mutation carriers suggests that RAD52 inhibitors may also be used to reduce breast cancer risk in BRCA1/2 mutation carrier." (PMID 32255263, 2020). "Recent studies showed that BRCA1-exon 11 constitutes an Ovarian Cancer Clustering Region (OCCR) since mutations located in this region are more associated with ovarian cancer risk than breast cancer." (PMID 33240314, 2020). "BRCA1/2-mutated tumors herald a higher risk of contralateral breast cancer." (PMID 33019612, 2020). "BRCA1-mutated basal-like breast cancer cells exhibited primary resistance to denosumab in mammosphere assays, thereby leading to an increased propensity in developing aggressive breast neoplasms and increasing the bone metastasis-initiation capacity of these cells." (PMID 32883003, 2020). "In addition to the well-known germline mutations, a smaller proportion of somatic mutations in BRCA1/2 genes (sBRCAm) were also found in primary ovarian and breast carcinomas." (PMID 32605126, 2020). "Furthermore, the histological grade of BRCA2-mutated breast carcinoma is generally lower than that of BRCA1-mutated breast carcinoma." (PMID 32269964, 2020). "Shortly thereafter, identification and cloning of the breast cancer susceptibility genes 1 and 2 (BRCA1 and BRCA2) took place and led to a marked expansion of our knowledge on genetic susceptibility, its function and impact on tumour biology, and both preventive and therapeutic interventions." (PMID 30915162, 2019). "BRCA1 is one of the best-known genes linked to breast cancer risk." (PMID 30874560, 2019). "Interestingly, a small number of losses were retained, including the Rb1-associated loss on chromosome 14, further supporting Rb1 as a collaborating driver in MYC-driven BRCA1-deficient mammary tumors." (PMID 30674894, 2019). "Moreover, the incidence of breast cancer rises quickly in early adulthood until age 30 to 40 years in BRCA1 mutation carriers." (PMID 31395037, 2019). "In female BRCA1 mutation carriers, the risk of developing breast cancer by the age of 80 is 72%." (PMID 31395037, 2019). "More research is needed to evaluate the effect of various chemotherapy regimens on survival in women with BRCA2-associated breast cancer, in particular with platinum-based regimens, which have shown preliminary evidence of effectiveness in BRCA1 mutation carriers." (PMID 30723304, 2019). "Furthermore, pathogenic variants towards the 3′-end of BRCA1 lead to a lower risk of ovarian cancer compared to breast cancer." (PMID 31395037, 2019).